OR10A3 (olfactory receptor family 10 subfamily A member 3)
Description:
Odorant receptor.
Synonyms: HTPCRX12; HSHTPCRX12
Tractability: Antibody: UniProt places it where antibodies can reach, with medium confidence; UniProt predicts a signal peptide or a membrane-spanning region; its Gene Ontology location is reachable by antibodies, with medium confidence.
Gene: Protein-coding gene on chromosome 11 (7,937,171 to 7,941,708, reverse strand). Ensembl gene ENSG00000170683.
Subcellular location: Cell membrane
Pathways (Reactome):
Sensory Perception: Expression and translocation of olfactory receptors
Gene Ontology:
Molecular function: olfactory receptor activity; G protein-coupled receptor activity
Biological process: detection of chemical stimulus involved in sensory perception of smell; sensory perception of smell; G protein-coupled receptor signaling pathway
Cellular component: plasma membrane; membrane
Genetic constraint (gnomAD): Loss-of-function variants: 17 observed, 16.16 expected, observed/expected ratio (o/e) 1.05, 90% interval 0.72 to 1.57. The upper end of that interval is the gene's LOEUF score, 1.57, which puts it in group 6 of 6, group 1 being the genes least tolerant of losing a copy. Missense variants: 398 observed, 387.22 expected, observed/expected ratio (o/e) 1.03, 90% interval 0.95 to 1.12. Synonymous variants: 145 observed, 150.43 expected, observed/expected ratio (o/e) 0.96, 90% interval 0.84 to 1.11.
Homologues: Orthologues: rabbit OR10A3 (86% identical), rat Or10a3 (83% identical), mouse Or10a3 (82% identical), mouse Or10a3b (80% identical), rat Or10a3c (80% identical), mouse Or10a3m (79% identical), rat Or10a48 (78% identical), mouse Or10a49 (77% identical), rat Or10a49 (77% identical), mouse Or10a3n (77% identical), mouse Or10a48 (74% identical). Paralogues in human: OR10A6 (85% identical), OR10A5 (58% identical), OR10A7 (55% identical), OR10A2 (55% identical), OR10A4 (53% identical), OR10C1 (49% identical), OR2F2 (46% identical), OR2F1 (46% identical), OR10H1 (45% identical), OR13C4 (45% identical), OR2D2 (45% identical), OR10AG1 (45% identical), and 80 more.
Diseases named in the same sentence as OR10A3 in open-access papers:
OR10A3 is named in the same sentence as 3 diseases in open-access papers, as found by Europe PMC text mining. Sharing a sentence is not in itself a finding about the gene and the disease. The quoted sentences say what the papers report.
atopic dermatitis (1 paper, 2015). "Most significant effects were found for two SNPs (rs110456748 and rs136792896) located at a distance of 23846 bp and 37742 bp from OR10A3 gene, known as being involved in atopic dermatitis, a common inflammatory skin disease." (PMID 25585689, 2015). "Among 25 significant markers, the highest effects were found for two SNPs (rs110456748 and rs136792896) located at the distance of 23846 bp and 37742 bp, respectively, from OR10A3 gene (olfactory receptor genes), known to be involved in atopic dermatitis in humans." (PMID 25585689, 2015).
cancer (1 paper, 2023). A tumor composed of atypical neoplastic, often pleomorphic cells that invade other tissues. "For the remaining genes, OR10A3, RPF1, KΑTNA1, and CES4A, in our risk score model, no specific relationship to cancer had been reported yet, further exploration should be carried out for their roles in the prognosis in DLBCL patients." (PMID 36816541, 2023).
OR10A3 also shares sentences with these, for which no sentence is quoted: inflammatory skin disease (1 paper).